INS (insulin)
Diseases named in the same sentence as INS in open-access papers (continued):
Sharing a sentence is not in itself a finding about the gene and the disease.
diabetes (continued). "At the end of the research, insulin sensitivity and fasting glucose were improved just through sleep prescription, thus demonstrating the value of this low-tech and low-cost approach to diabetes preventions." (PMID 30841553, 2019). "This phenomenon has been described in insulin-treatment naïve people presenting with hypoglycaemic episodes (described as insulin autoimmune syndrome (IAS) or Hirata disease) as well as in patients with labile diabetes treated with modern genetically engineered insulin analogues." (PMID 30514969, 2019). "Diabetes mellitus (DM) is a metabolic disorder characterized by chronic hyperglycemia together with disturbances in the metabolism of carbohydrates, proteins and fat, which in general results from an insulin availability and need imbalance." (PMID 31658729, 2019). "However, although this method is considered the gold standard for estimation of insulin sensitivity, many studies disagree on the role of hepatic and peripheral insulin sensitivity in contributing to diabetes remission after surgery." (PMID 30679147, 2019). "Similar to other metabolic tissues, BAT becomes less sensitive to insulin during (pre)diabetes." (PMID 31416197, 2019). "Previous studies have shown that miR-7 could suppress secretion of insulin, indicating that it might become a new target for improving β cell function in diabetes." (PMID 30728764, 2019). "This is currently not done in clinical practice but could be achieved with an “EPO pump” similar to the programmable insulin pumps used to treat diabetes mellitus." (PMID 31630225, 2019). "Hyperinsulinemia may be targeted by diet alterations or via re-positioning diabetes drugs such as the insulin-sensitizing drug metformin as adjuvant ADT therapy, to reduce circulating ligand levels." (PMID 31379747, 2019). "Since the snail insulins do not form clusters and should act faster than currently available insulin drugs, they may lead to better or new diabetes treatments." (PMID 30747102, 2019). "Nonetheless, we observed that in individual mice both insulin and proinsulin rose prior to diabetes onset, suggesting progressive β cell dysfunction, and declined following diabetes onset, likely as a consequence of the β cell death indicated by a rise in circulating miR-375 levels." (PMID 30842440, 2019). "Future research could extend this proof-of-concept Q-learning model to include other types of insulin and other types of diabetes medications and other state variables." (PMID 31464196, 2019). "Therefore, we conducted a survey to characterise the prescribing practices of specialist diabetes healthcare professionals in this region and assessed factors that influence clinical decision-making regarding insulin initiation in T2D." (PMID 30993528, 2019). "Therefore, identifying the regulatory mechanism of glucagon secretion and insulin resistance in pancreatic α cells can contribute to the elucidation of the pathophysiology of diabetes." (PMID 31357734, 2019). "More evidence is demonstrating the potential for embryonic stem cells, adult stem cells, and progenitor cells to produce β cells with the ability to produce insulin, reduce glucose levels in animal models, and to some extent, reverse diabetes symptoms through pancreatic regeneration." (PMID 30820250, 2019). "Common therapies for diabetes involve the administration of exogenous insulin." (PMID 30893335, 2019). "Within our set of medical Sleeping Beauties one SB stands out, the Matthews SB-SNPR, published in 1985, on a mathematical, computerized model to determine plasma glucose and insulin concentrations, a method which turned out to be of great significance for diabetes patients." (PMID 31626673, 2019). "Patients can receive ICPI in parallel with initiation of insulin therapy and management of their diabetes, except in severe cases where ICPI could be delayed by a few days." (PMID 30400055, 2019).
diabetes (continued). "Due to the great therapeutic effect towards achieving optimal glycemic control in Type 2 DM patients as compared to oral hypoglycemic agents, insulin therapy has been recognized as the foundation of diabetes care and is aggressively being prescribed by physicians in Malaysia." (PMID 31514391, 2019). "Recent data suggest differences UCP2 expression driven by common polymorphisms in the UCP2 promoter region may play a critical role in insulin secretion and ultimately the development of diabetes." (PMID 31706320, 2019). "Early-phase insulin secretion plays an important role in the development of diabetes." (PMID 31772943, 2019). "To determine whether diabetes in early overnutrition mice was due to increased apoptosis of β cells, we quantified insulin immunoreactive cells that colocalized with cleaved caspase-3, a specific marker for cells undergoing apoptosis." (PMID 30842440, 2019). "Previous studies have suggested that the balance between lipogenesis and lipolysis in pregnancies complicated by diabetes may be affected by maternal insulin concentrations." (PMID 31575970, 2019). "Treatment may also include management of organ specific issues e.g. thyroxine in thyroid-related disease, insulin in diabetes mellitus, pancreatic enzyme replacement in pancreatic insufficiency." (PMID 31555465, 2019). "Additionally, black and white children with insulin-treated diabetes showed T2D-related symptoms in terms of obesity, irrespectively of their autoimmunity, further highlighting the ethnicity-dependent, heterogeneous pathogenesis mechanisms." (PMID 31685799, 2019). "High burden of obesity, use of illicit drugs, poor insulin compliance could be a potential reason for the high rate of decompensated diabetes among blacks." (PMID 31192058, 2019). "Higher scores of anxiety and depression were statistically significant in female gender, older participants, individuals with longer duration of diabetes, those taking non-insulin treatment, and individuals with painful neuropathy, nephropathy, and foot ulcers." (PMID 31131177, 2019). "Of the known diabetics, 25.1% are on insulin therapy, which is equivalent to 404,619 people." (PMID 31652253, 2019). "Another important finding in our study is that the cut-off (≤0.20 nmol/mmol) for a differential diagnosis of diabetes is also helpful in identifying patients who need insulin or secretagogue therapy added to their treatment regimen to achieve their goal of glucose control." (PMID 31485449, 2019). "The studies have demonstrated that ginger and its bioactive compounds could protect against diabetes mellitus and its complications, probably by decreasing the level of insulin, but increasing the sensitivity of insulin." (PMID 31151279, 2019). "When comparing the Spearman correlation coefficient for insulin in the same gender, between control subjects and diabetics, we found that for both men and women, there is a null correlation, but in the case of women, the distribution is in the opposite direction." (PMID 31314811, 2019). "Impairment of insulin protein level induced muscle wasting in STZ diabetes-like mouse model." (PMID 31327904, 2019). "Statins could lead to diabetes by increasing insulin resistance, impairing beta cell function or a combination of these two processes." (PMID 31455371, 2019). "Diabetes nurses provide one-on-one education to patients in Canada, whereas at Renji Hospital in Shanghai they run weekly patient classes on diet, exercise, psychology, insulin injections and blood sugar monitoring." (PMID 30949256, 2019). "Given the reduced Mc4r expression in the STZ treated mice, we hypothesized that enhancing MC4R signaling via MTII administration may improve the counterregulatory response to insulin induced hypoglycemia in diabetes." (PMID 30503832, 2019).
diabetes (continued). "Previous studies have indicated that vaspin acts as an insulin sensitizer with anti-inflammatory effects and might serve as a compensatory mechanism in the pathogenesis of visceral obesity, type 2 diabetes mellitus (T2DM), and atherosclerosis." (PMID 30909620, 2019). "NOX4 activation during the onset of insulin resistance is likely increased to enhance vascular hyperpolarizing effects and insulin signaling effects; whereas advanced diabetes progression hampers the beneficial effects of NOX4, with oxidative stress instead being induced." (PMID 31382355, 2019). "Furthermore, the DES total score was related to the daily insulin use calculated per day and per patient body weight, i.e., the lower the insulin dose, the higher the diabetes empowerment (DES score; r = -0.22, p = 0.01)." (PMID 31183368, 2019). "Insulin and different types of oral antidiabetic drugs are used in the treatment of diabetes." (PMID 31370156, 2019). "Those who are members of diabetes association had 3 times increased odds of having a favorable attitude on insulin self-administration than those who are not." (PMID 31915711, 2019). "Therefore, further investigations aimed to delineate other mechanisms of IF, particularly for humans who are incapable of adipose tissue browning or are insulin resistant (e.g. ageing and diabetes) are warranted." (PMID 30792482, 2019). "Membership of Ethiopian Diabetes Association (EDA) was significantly associated with adherence to insulin therapy compared to the non-members." (PMID 31692777, 2019). "Similarly, with low calorie, inulin lowers the blood lipid and blood glucose level, as well as exerts a non-insulin-dependent therapeutic effect on diabetes through increasing the total antioxidant capacity and superoxide dismutase activities." (PMID 31687407, 2019). "FDKP as a carrier material prepared insulin lung powder inhalation not only possess good reproducibility but also has good atomization performance and effective pulmonary deposition, which is an effective therapy for the diabetes treatment." (PMID 31257946, 2019). "The hallmark of diabetes is the high levels of blood glucose in the body (hyperglycemia), which occurs because the body can not produce enough insulin (type 1 diabetes) or use insulin effectively (type 2 diabetes)." (PMID 31159842, 2019). "Type 1 diabetes (T1D), defined also as insulin-dependent diabetes mellitus, is a multifactorial disorder characterized by the organ-specific autoimmune destruction of pancreatic insulin producing beta cells in human leukocyte antigen (HLA) genetically predisposed subjects." (PMID 31540445, 2019). "Thiazide diuretic use has been associated with altered glucose homeostasis (through attenuated insulin secretion), although a large prospective study found no increased diabetes risk with thiazide diuretics." (PMID 30920624, 2019). "Our study uncovered similar concerns, and contributes to the evidence based with the new additional finding that these concerns may apply to diabetes-specific medications such as insulin." (PMID 31238950, 2019). "As the most common drugs for diabetes mellitus, synthetic compounds can also be classified into several categories according to their working mechanisms, such as insulin secretion promotor agents, insulin sensitizer agents, α-glucosidase inhibitors, and so forth." (PMID 31214029, 2019). "Regarding their diabetes medication; 184(43.7%) were on insulin." (PMID 31455263, 2019). "Therefore, new strategies for insulin and insulin analog production are urgently required, in order to increase the availability of therapeutic products for containing the diabetes epidemic." (PMID 31798448, 2019). "Additionally, multiple signaling pathways associated with metabolism and diabetes/hyperglycemia were enriched with target genes of these four miRNAs, such as sphingolipid, cGMP-PKG, FoxO, AMPK, Rap1, and insulin signaling pathways." (PMID 31582977, 2019).
diabetes (continued). "Nevertheless, when splenocytes from disease-protected animals using insulin peptide-loaded tolDCs were retested for their regulatory potential in the adoptive NOD-SCID co-transfer model, they caused more rapid and a 100% onset of diabetes compared to controls." (PMID 31139178, 2019). "A notable trend found in this study is that more patients receiving CO islets were insulin independent at 6 months post transplantation, evident in the observation that 37.5% CO (three in eight) patients who were diabetes free pre-op remained insulin independent at 6 months post TP-IAT." (PMID 31885286, 2019). "The UK Prospective Diabetes Study Group demonstrated that although both metformin and insulin therapies similarly improved blood glucose levels in patients with type 2 diabetes, patients who were treated with metformin benefited more in terms of clinical outcome than those on insulin treatment." (PMID 31089886, 2019). "Treatment of diabetes, e.g. insulin, could interfere with HOMA-IR calculations, but we excluded all diabetic patients and controls." (PMID 31345181, 2019). "Increased insulin sensitivity may alter insulin and/or sulphonylurea requirements post-exercise for those with diabetes." (PMID 31161377, 2019). "With the technological and therapeutic advances, as well as new knowledge about the psychological and social factors related to the disease, T1DM treatment is currently based on the triad insulin, monitoring and education on diabetes (which includes healthy eating and regular physical activity)." (PMID 31826155, 2019). "So the best way I’ve managed my diabetes is through the insulin pump”." (PMID 31166971, 2019). "Thus, some exosomal miRNAs are pathological factors in diabetes by targeting key proteins and acting as crucial modulators of insulin sensitivity." (PMID 31398847, 2019). "Several other genes displaying inverted correlations have previously been linked to diabetes (7/18), either by functional studies (TRIB1, glucose metabolism; NFKBIA, insulin resistance pathway) or as candidate disease genes in GWAS or gene expression studies (TMPPE, PRTG, and ZNF319)." (PMID 31159854, 2019). "Diabetes is caused by a failure of the pancreas to produce insulin (type I diabetes) or by insulin resistance (cells do not respond to insulin; type II diabetes)." (PMID 30875760, 2019). "Medications prescribed among the cohort of participants at risk of CKD were generally similar to the CKD cohort, except for more common use of insulin (83 363 [16.3%]) among those with diabetes and of NSAIDs (701 493 [35.5%]) and PPIs (295 804 (15.0%]) overall (eTable 6 in the Supplement)." (PMID 31860111, 2019). "Indeed, numerous factors contribute to this relationship, such as the duration of diabetes, HbA1c, background treatment, complications, accompanying diseases, β‐cell function, the timing and duration of insulin therapy, and the stage of DR." (PMID 30973204, 2019). "However, a decrease in beta cell mass or impaired beta cell function can lead to abnormal plasma insulin levels that can promote glucose intolerance and diabetes." (PMID 31231496, 2019). "The idea that increase insulin content can give rise to the fallacious impression of b-cell production has also been suggested for islets from patients with diabetes and rodent models of diabetes." (PMID 30805033, 2019). "Type 2 DM is a non-insulin-dependent or adult onset of diabetes." (PMID 30962863, 2019). "In addition, improving access to blood glucose monitoring equipment and supplies is needed, particularly for adults with T2D who are learning diabetes self-management skills or those treated with insulin." (PMID 31443659, 2019).
diabetes (continued). "Neurodegeneration in diabetes is mediated by multiple neuropathogenic factors including hyperglycemia mediated damage, but also hypoglycemic episodes, cerebrovascular alterations or insulin derregulation in the brain or among others." (PMID 31126031, 2019). "This study provides evidence of increased glycemic control and patient satisfaction coupled with decreased total insulin requirements and diabetes costs in patients with T2DM initiating V-Go for insulin delivery compared with patients continuing standard insulin delivery." (PMID 32685581, 2019). "Insulin plays a central role in the very prevalent human disease, diabetes mellitus." (PMID 31590432, 2019). "Our key findings are presented in terms of the five pillars of the BoP: increased awareness of diabetes; early diagnosis of diabetes; access to quality care by trained health-care professionals; stable and affordable insulin supply; and improved self-management through patient education." (PMID 31116677, 2019). "Our findings suggest that agents that reduce somatostatin action (SSTR antagonists) or secretion (SGLT2 inhibitors) might be useful as adjuncts to insulin in diabetes therapy." (PMID 30635569, 2019). "Insulin pump therapy is a widely used treatment method for diabetes for patients of all ages." (PMID 30239214, 2019). "For example, insulin is widely used for the management of diabetes." (PMID 31119124, 2019). "FFE supplementation is a promising nutritional intervention for the management of acute postprandial glucose and insulin homeostasis, and it is a possible adjunctive treatment for glycemic management of chronic metabolic disorders such as prediabetes and type 2 diabetes mellitus." (PMID 31370154, 2019). "Recently, artificial pancreas (AP) systems are emerging and they use machine-learning algorithms to reduce the frequency of hypoglycemic episodes, even in the presence of intensive insulin treatment, and are among the greatest advances in diabetes care in recent development." (PMID 31694629, 2019). "In Canada, diabetes practice guidelines recommend antidiabetic agents (including insulin) and cardioprotective therapies (antihypertensives, notably ACE inhibitors and angiotensin-receptor blockers (ARB), and lipid-lowering agents, notably statins) for individuals aged ≥55 with diabetes." (PMID 31805662, 2019). "Some studies showed that IGF-1, a hormone similar in molecular structure to insulin and highly present and secreted in osteoblasts, significantly decreased in diabetes patients and animals, which could lead to the acceleration of bone resorption." (PMID 31443143, 2019). "The Diamond solution provides diabetes self-management by enabling patients to send details about their blood sugar readings at specific times to their nominated care coordinator to receive recommendations for diet and exercise and insulin titration." (PMID 31066699, 2019). "Participants with DKD had older age, longer duration of diabetes, higher proportion of using insulin, having comorbid hypertension, CAD, stroke, DR, higher levels of BMI, SBP, HbA1c, TG, HDL-C, non-HDL-C, and lower level of eGFR than those without DKD (P < 0.05)." (PMID 30658647, 2019). "However, during diabetes Pomc was elevated in the hindbrain, perhaps suggesting a counter-regulatory effect and intact insulin and/or leptin signalling up to this point in the pathway." (PMID 31601900, 2019). "Thus, CPT not only significantly ameliorated lipid metabolism and insulin responsiveness but also decreased hepatic inflammation in diabetes." (PMID 31404259, 2019). "Moreover, the cross-sectional nature of this study limits its power to establish a causal association between glycemic control measures and the use of insulin pens in patients with diabetes." (PMID 31461470, 2019).